PBK (PDZ binding kinase)
Description:
Phosphorylates MAP kinase p38. Seems to be active only in mitosis. May also play a role in the activation of lymphoid cells.
Synonyms: CT84; SPK; TOPK; FLJ14385; Nori-3; HEL164
Tractability: Small molecule: a high-quality ligand is known; it belongs to a druggable protein family. PROTAC: UniProt records ubiquitination sites on it; ubiquitination databases record sites on it; its protein half-life has been measured; a small molecule that binds it is known.
Target class: Enzyme; Protein Kinase; Other protein kinase TOPK family; Other protein kinase group; Kinase
Gene: Protein-coding gene on chromosome 8 (27,809,621 to 27,838,082, reverse strand). Ensembl gene ENSG00000168078.
Subcellular location (Human Protein Atlas): Cytosol
Gene Ontology:
Molecular function: protein binding; protein serine/threonine kinase activity; ATP binding; MAP kinase kinase activity; protein kinase activity; protein serine kinase activity; protein tyrosine kinase activity
Biological process: mitotic cell cycle; MAPK cascade
Cellular component: nucleus
Genetic constraint (gnomAD): Loss-of-function variants: 2 observed, 5.94 expected, observed/expected ratio (o/e) 0.34, 90% interval 0.14 to 1.06. That is too few expected variants to judge how well the gene tolerates losing a copy. Missense variants: 71 observed, 80.06 expected, observed/expected ratio (o/e) 0.89, 90% interval 0.73 to 1.08. Synonymous variants: 20 observed, 25.47 expected, observed/expected ratio (o/e) 0.79, 90% interval 0.55 to 1.14.
Homologues: Orthologues: chimpanzee PBK (99% identical), macaque PBK (97% identical), dog PBK (94% identical), rabbit PBK (92% identical), pig PBK (92% identical), rat Pbk (91% identical), guinea pig PBK (89% identical), mouse Pbk (88% identical), tropical clawed frog pbk (70% identical), zebrafish pbk (66% identical), Drosophila melanogaster CG8173 (43% identical).
Diseases named in the same sentence as PBK in open-access papers:
PBK is named in the same sentence as 141 diseases in open-access papers, as found by Europe PMC text mining. Sharing a sentence is not in itself a finding about the gene and the disease. The quoted sentences say what the papers report.
lung carcinoma (51 papers, 2013 to 2026). "The expression of PBK has been associated with the prognoses of lung cancer, colorectal cancer and gastric cancer." (PMID 36769187, 2023). "PBK has been described in some human cancers and its overexpression is associated with tumor invasion, proliferation, and metastasis in OV, lung cancer, COAD, and PRAD." (PMID 34859058, 2021). "Several previous reports have linked increased expression of PBK to various cancers including lymphoma, leukemia, melanoma, colorectal cancer, breast cancer, lung cancer and cholangiocarcinoma, but PBK expression has not been reported in GBM." (PMID 26081429, 2015). "Although few samples had mutations in PBK, we observed that mutations in CNV accounted for the majority of PBK gene DNA alterations in all lung cancer patients and found a high proportion of LUAD patients with CNV with multiple tumor suppressor genes, such as CCDC25, SCARA5 and EPHX2." (PMID 37993518, 2023). "Indeed, recent work by Matsuo and associates show that a novel inhibitor of PBK/TOPK was sufficient to induce complete regression of tumors in a lung cancer xenograft model." (PMID 25909225, 2015). "PBK is associated with poorer prognosis in lung cancer, is up-regulated in IDC relative to DCIS at the transcriptomic level, and may be a promising molecular target for treatment of breast cancer." (PMID 23547718, 2013). "Previous studies indicated that overexpression of PBK increases the cell proliferation and tumorigenesis in JB6 epidermal cells in vivo and in vitro, while knockdown of PBK suppresses tumor growth of lung cancer cell lines." (PMID 38215156, 2024). "The ROC curves demonstrated good diagnostic efficacy for lung cancer, with AUC values of 0.962, 0.924, 0.886, and 0.95 for the four hub genes CENPF, AURKA, PBK, and CCNB1, respectively." (PMID 36984548, 2023). "Patients with high PBK expression had poor prognosis and high tumor recurrence rate, suggesting that PBK is a predictor of lung cancer prognosis." (PMID 36110946, 2022). "Previous studies have suggested that TOPK/PBK promotes cell migration through regulation of the PI3K/PTEN/AKT pathway in lung cancer." (PMID 34066486, 2021). "PBK has a high trans-activity, plays a crucial role in various cancers, and also promotes migration and invasion of lung cancer cell." (PMID 33771165, 2021). "PBK is overexpressed in malignant tumors including Ewing sarcoma, lymphoma, leukemia, melanin tumors, and breast and lung cancers." (PMID 34094915, 2021). "Previous studies have shown that the therapeutic effect in lung cancer through inhibiting PBK/TOPK signaling pathway." (PMID 30898980, 2019). "We used three lung cancer cell lines H441, H1975, and H1299 with high, middle, and low expression level of PBK/TOPK, respectively." (PMID 30898980, 2019). "Previous studies indicated that PBK/TOPK is highly expressed in several malignancies, especially in lung cancer." (PMID 30898980, 2019). "Taken together, baicalin can inhibit proliferation of lung cancer cells as a PBK/TOPK inhibitor both in vitro and in vivo." (PMID 30898980, 2019). "Many studies have shown overexpression of PBK/TOPK in malignancies such as Ewing sarcoma, lymphoma, leukemia, melanoma, breast cancer, lung cancer, cholangiocarcinoma, and CRC." (PMID 30286126, 2018). "The overexpression of PBK was revealed as a unfavorable factor for overall survival of patients with lung cancer, gastric cancer and nasopharyngeal carcinoma." (PMID 28525379, 2017). "Overexpression of miR-770-5p induced apoptosis, and elevation of miR-770-5p sensitized MCF7 breast carcinoma and A549 lung carcinomas to IR through direct targeting of PBK." (PMID 28333152, 2017). "In lung cancer, PBK promoted the phosphorylation of AKT, but decreased the expression of PTEN to facilitate the cell migration and invasion." (PMID 28525379, 2017).
lung carcinoma (continued). "Our results are in good agreement with two earlier studies of lung cancer where either 59% or 54% of stage III-IV lung cancer samples were shown to have PBK/TOPK expression." (PMID 25909225, 2015). "PBK is overexpressed in multiple types of cancer, including breast, prostate, colon, bladder, and lung cancer, but is undetectable in normal tissues except germ cells in the testis and several fetal tissues." (PMID 25745361, 2015). "Multiple studies have found that PBK overexpresses in breast, prostate, colon, bladder, and lung cancers and is a prognostic biomarker for poor outcomes." (PMID 25745361, 2015). "Baicalin might inhibit proliferation of lung cancer cells as a PDZ-binding kinase/T-LAK cell-originated protein kinase (PBK/TOPK) inhibitor both in vitro and in vivo." (PMID 33585556, 2020). "PBK promotes migration in lung cancer by modulating the PI3K/AKT pathway." (PMID 32098194, 2020). "Previous studies revealed that PBK/TOPK is highly expressed in human lung cancer." (PMID 30898980, 2019). "Therefore, inhibitors of PBK/TOPK would be expected to be an excellent drug target for cancer chemotherapy treatment of lung cancer." (PMID 30898980, 2019). "Previous studies showed that PBK/TOPK was highly expressed in multiple types of cancers and associated with poor prognosis, such as lymphoma, leukemia, melanoma, colorectal, breast and lung cancers, and cholangiocarcinoma." (PMID 30898980, 2019). "In lung cancer, patients with high expression of PBK/TOPK have poor clinical outcome." (PMID 27347940, 2016). "Although PBK, RRM2, and DLGAP5 are also significant in cancer biology, EXO1’s potential impact on lung cancer mechanisms and treatment is particularly noteworthy." (PMID 39777332, 2024). "The PBK inhibitor OTS964/OTS514 was shown to inhibit cytokinesis and cancer cell growth, and OTS964/OTS514 induced the apoptosis of lung cancer cells including small cell lung cancer (SCLC) cells." (PMID 34859058, 2021). "Herein, for the first time, we found that baicalin can target PBK/TOPK kinase directly and inhibit the proliferation of lung cancer." (PMID 30898980, 2019). "PBK/TOPK overexpression was significantly correlated with poor prognosis and served as a prognostic marker for lung cancer." (PMID 30898980, 2019). "In short, the result of present studies identified that PBK/TOPK was a direct and important target of baicalin for inhibition of lung cancer proliferation and transformation." (PMID 30898980, 2019). "PBK, also known as TOPK, is a potential therapeutic target in lung cancer that promotes cell migration by modulating a PI3K/PTEN/AKT-dependent signaling pathway." (PMID 31726467, 2019). "Lung cancer patients’ prognoses are often foreseen using matched prognostic models, and genes CENPF, AURKA, PBK, and CCNB1 in lung cancer may serve as therapeutic targets, which require further investigations." (PMID 36984548, 2023). "In addition, a previous study reported that CCNA2, CDC20, PBK, and TOP2A that interacted with CDK1 play vital roles in survival outcomes in human lung cancer." (PMID 32426332, 2020). "Baicalin can target PBK/TOPK protein kinase directly and inhibit the proliferation of lung cancer." (PMID 30898980, 2019). "High PBK expression, either alone or in combination with a low level of PTEN, may serve as a prognostic marker for lung cancer." (PMID 31726467, 2019).
breast carcinoma (42 papers, 2013 to 2026). "The aberrant expression of AURKA, BUB1B, CCNA2, CCNB2, and PBK resulted in a poorer survival rate of breast cancer patients in the high-risk group having a survival rate of less than 2 years." (PMID 36980449, 2023). "Using multivariate Cox regression analysis, we confirmed that PBK/TOPK was an independent risk factor for the prognosis of patients with breast cancer (P = 0.034)." (PMID 36171591, 2022). "Our findings further support the role of PBK as a marker of poor prognosis in breast cancer, with expression of PBK also associated with the histological markers of proliferation, Ki67 and tumour grade." (PMID 23547718, 2013). "In one of the latest studies, it was reported that the overrepresentation of the PBK gene resulted in a poor prognosis of patients suffering from breast cancer." (PMID 36980449, 2023). "The five potential prognostic biomarkers, i.e., Aurora Kinase A (AURKA), BUB1 Mitotic checkpoint serine/threonine kinase B (BUB1B), Cyclin A2 (CCNA2), Cyclin B2 (CCNB2), and PDZ binding kinase (PBK) were upregulated in breast cancer." (PMID 36980449, 2023). "AURKA, BUB1B, CCNA2, CCNB2, and PBK, and these hub genes obtained were found to be upregulated (based on log2fold change value) in breast cancer." (PMID 36980449, 2023). "Previous studies have found that CENPF, MELK, PBK, TOP2A and NEK2 are upregulated in breast cancer and this is associated with a poor prognosis." (PMID 36776306, 2023). "In the case of breast cancer, the PBK gene was found to be overexpressed, and this resulted in the progression and probable metastasis of breast cancer to form GBM and HCC." (PMID 36980449, 2023). "Elevated expression of the five hub genes AURKA, BUB1B, CCNA2, CCNB2, and PBK are related to poor OS in breast cancer patients." (PMID 36980449, 2023). "PBK/TOPK protein is overexpressed in breast cancer, and its expression is closely related to the clinicopathological characteristics of the disease." (PMID 36171591, 2022). "PBK/TOPK is overexpressed in breast cancer, and the expression is closely related to the clinicopathological characteristics of the disease." (PMID 36171591, 2022). "Immunohistochemical staining was used to detect the expression of PBK/TOPK in 202 cases of breast cancer tissues." (PMID 36171591, 2022). "The finding that PBK/TOPK protein overexpression predicts poor prognosis for patients with breast cancer is consistent with a previous study and other prognostic studies on other malignancies." (PMID 36171591, 2022). "PBK is a serine/threonine kinase, and its expression is elevated in breast cancer, prostate cancer, and CRC." (PMID 35637462, 2022). "The OS and DFS of breast cancer patients with high expression of PBK/TOPK are shortened in the present study, indicating that PBK/TOPK expression is correlated with the prognosis of malignant tumors." (PMID 36171591, 2022). "For patients with stage 3 breast cancer, the expression level of PBK/TOPK was negatively correlated with OS as well." (PMID 36171591, 2022). "Kaplan-Meier analysis revealed that the expression level of PBK/TOPK was negatively correlated with the OS of breast cancer patients." (PMID 36171591, 2022). "PDZ-binding kinase/T-lymphokine-activated killer cell-derived protein kinase (PBK/TOPK) is a potential prognostic indicator for patients with breast cancer." (PMID 36171591, 2022). "As expected, several of the genes associated with top differentially methylated probes between these groups have been previously implicated in breast cancer, including SDC2, PBK, ALOX12B, DAG1, ZNF382, and FST." (PMID 35564499, 2022). "High expression of PBK/TOPK was an independent influential factor on OS in breast cancer (P = 0.034), and HER-2 expression was an independent influential factor on DFS (P = 0.014)." (PMID 36171591, 2022).
breast carcinoma (continued). "The objective of the present study was to explore the relationship between PBK/TOPK expression and clinicopathological indicators as well as the survival of patients with breast cancer." (PMID 36171591, 2022). "In this retrospective study, we explored PBK/TOPK protein expression in patients with breast cancer." (PMID 36171591, 2022). "Only slides stained immunohistochemically to detect the expression of PBK/TOPK protein in paraffin tissue samples of breast cancer were included in the final analysis." (PMID 36171591, 2022). "PBK/TOPK protein is difficult to detect in normal breast tissues but has been found in breast cancer tissues." (PMID 36171591, 2022). "Despite the oncogenic potential of PBK, the authors report that miR-770-5p can directly target PBK in radiation response, confers radiosensitivity to breast cancer." (PMID 34804940, 2021). "PBK is a serine-threonine kinase that was reported upregulated in breast cancer, and server as a therapy target for breast cancer." (PMID 33403046, 2021). "This study shows that hub genes associated with breast cancer pathogenesis, namely RRM2, TOP2A, PBK, MELK, and NUSAP1, are gradually upregulated from NME to DCIS and then downregulated in IDC." (PMID 34094915, 2021). "Five hub genes, RRM2, TOP2A, PBK, MELK, and NUSAP1, which are associated with breast cancer pathogenesis, are gradually upregulated from NME to DCIS and then downregulated in IDC." (PMID 34094915, 2021). "Hub genes, namely TOP2A, MELK, PBK, NUSAP1, and RRM2, are closely associated with the occurrence and pathogenesis of breast cancer." (PMID 34094915, 2021). "Lee and colleagues discovered that miR-770-5p radiosensitizes breast cancer cells by targeting PDZ-binding kinase (PBK)." (PMID 34804940, 2021). "PBK has emerged as a key player in multiple tumour types, including breast cancer, haematological malignancies, cervical cancer and bladder carcinoma." (PMID 30237440, 2019). "PBK/TOPK has been identified as prognostic markers for patients with leukemia, non-small cell lung cancer, colorectal cancer, and breast cancer." (PMID 27347940, 2016). "As PBK is a biomarker for poor prognosis in breast cancer and plays a critical role in mitosis, we wonder if atorvastatin-induced cytotoxicity involving down-regulation of PBK gene expression." (PMID 25745361, 2015). "Our studies therefore identified PBK as a down-stream effector of geranylgeranylation signaling and a target gene of YAP, and defined a PBK signaling pathway activated by geranylgeranylation and the Hippo signaling for breast cancer growth." (PMID 25745361, 2015). "PBK phosphorylates histone H3 at Ser10 in vitro and in vivo, and to function as molecular marker in breast cancer." (PMID 25745361, 2015). "PBK has been identified as a kinase regulating mitosis by phosphorylation of GPSM2 (G-protein signaling modulator 2) in breast cancer cells." (PMID 25745361, 2015). "Direct knockdown of PBK by shRNA or inhibition of PBK activity by its kinase inhibitor severely impaired breast cancer cell proliferation." (PMID 25745361, 2015). "Taken together, we conclude that PBK mediates geranylgeranylation signaling-promoted breast cancer cell proliferation." (PMID 25745361, 2015). "A 3-marker signature comprised of high PBK, high ANLN and low PDZK1 expression was associated with decreased recurrence-free survival (p < 0.001) and breast cancer-specific survival (BCSS) (p < 0.001)." (PMID 23547718, 2013).